IL7 (interleukin 7)
Diseases named in the same sentence as IL7 in open-access papers (continued):
Sharing a sentence is not in itself a finding about the gene and the disease.
infection (continued). "Since homeostatic IL-7 expression in the gut is mostly restricted to epithelial cells, it is possible that these cells, which are often the first targets of enteric pathogens, could also be producing IL-7 in response to infection, as evidenced in the C. rodentium-infected colon." (PMID 28579989, 2017). "After 4 days of infection with X4-tropic NL4.3-wt (p < 0.01 and p < 0.001), the efficiency of proviral integration increased 60- and more than 500-fold in CCL19 and IL-7-treated cells, respectively." (PMID 28539614, 2017). "Quantifying both mRNA and protein in tissues, we demonstrated a transient increase of IL-7 expression in the small intestine of SIV-infected rhesus macaques, starting with local detection of the virus by day 3 of infection." (PMID 28579989, 2017). "There were significant differences in the levels of IFN-α, IFN-γ, IL-6, IL-7, IL-8, IL-10, IL-12p70, IP-10, MCP-1, sCD40L and VEGF in patients with DI, DW or SD infections." (PMID 26982706, 2016). "The levels of IFN-α, IFN-γ, IL-7, IL-12p70, MCP-1 and sCD40L in SD of primary cases were comparable with DI, DW and SD of secondary infections." (PMID 26982706, 2016). "The most important observation was that IFN-α, IFN-γ, IL-7, IL-12p70, MCP-1 and sCD40L were significantly reduced in secondary infections." (PMID 26982706, 2016). "Rapid and more-sustained elevations in IL-1ra, MIP-1α, IL-5, IL-10 and IL-17 levels were followed by IL-1β, IL-2, IL-7, IL-9, IL-12, IL-15, IFN-α2, MIP-1β, FGF-2 and GM-CSF at over 2 months post-infection, and accompanied by the recovery of CD4+ cells." (PMID 27830756, 2016). "We have analyzed transduction efficiencies (multiplicity of infection (m.o.i.)= 1) following stimulation of naïve T cells for 48 h with magnetic anti-CD3/CD28 beads and IL-7, IL-15 and IL-21." (PMID 27435312, 2016). "This suggests that IL-7 treatment and SAMHD1 knockdown lead to silent infection events in resting CD4+ T cells, and, thus, an underestimation of the latently infected cell population." (PMID 26067822, 2015). "We found no activation or even reduction in base-line expression for multiple molecules (IL-7, IL-4, IL-13, GATA3, ROR-γt, and CXCL12) at 2, 6 and 10 days post-infection." (PMID 25254971, 2014). "The significant elevation of IFN-γ, but a reduction of IL-7, at 2 dpi suggested dysregulated ILC subsets at early stages of infection." (PMID 25254971, 2014). "For HIV-1BaL-infected lymphoid tissues, IL-7 increased Bcl-2 expression in HIV-1-infected CD4+ T cells 2.2±0.2 fold and 2.6±0.2 fold on day 6 and 9 post infection, respectively (n = 6, p<0.001)." (PMID 23408885, 2013). "In HIV-1LAI.04-infected lymphoid tissues, IL-7 25 ng/mL increased Bcl-2 expression in HIV-1-infected CD4+ T cells on average 2.3±0.1 fold and 2.4±0.1 fold on day 6 and 9 post infection, respectively (n = 8, p<0.0001)." (PMID 23408885, 2013). "IL-7 and CD3/28 treatments were able to overcome this block and resulted in both higher levels of envelope protein and spreading infection." (PMID 22911005, 2012). "In particular, the levels of IL-7 and IL-15 obtained after MVA and MVA-B infection were approximately 100 fold higher than after mock-infection without maturation cocktail." (PMID 21625608, 2011). "Although IL-7 can be utilized by memory T cells for survival, the observation that in chronically infected mice there were more IL-7Rα− effector cells two months after infection suggests that a sub-population in infected mice may depend instead on antigen or infection for maintenance." (PMID 21124875, 2010). "A decrease in the percentage of IL-7(+) cells and an increase in the percentage of IL-16(+) cells in the MLN indicated that secretion of these cytokines was also altered after LP-BM5 infection." (PMID 16584110, 2005). "The concentration of IL-7 was not affected by the source of infection or the type of bacteria involved." (PMID 40005375, 2025).
infection (continued). "Notably, the pulmonary levels of several cytokines and chemokines exhibited a secondary increase at days 21 or 28 post-infection (MIP-1⍺, MCP-1, IL-7, IL-10, IP-10, IL-2, and GM-CSF)." (PMID 39066335, 2024). "After resolution of infection, resident memory T cells (TRM) form and disperse in the skin to provide protective immunity and are particularly dependent on epithelial-derived factors, such as IL-7 and IL-15, supplied by keratinocytes." (PMID 37946298, 2023). "However, expression of specific fibromodulatory interleukins (e.g., IL7, IL15, and IL20) was enhanced only in Chlamydia-infected HCECs, suggesting a cell type-specific response to infection." (PMID 37874141, 2023). "The cytokines retrieved from M9809 gene set of Molecular Signatures Database in Gene Set Enrichment Analysis (GSEA), such as IL-7, CCL2, CXCL10 and IFNs, were significantly up-regulated in cerebral cortex, but markedly down-regulated in cerebellum and right ventricle post infection." (PMID 35377064, 2022). "HIV-1-induced CD69 upregulation was abrogated by suppressing infection with the fusion inhibitor T20 or by treating cells with ruxolitinib, which blocks IL-7-mediated JAK-STAT signaling, demonstrating that the enhanced CD69 induction requires both infection and cytokine signaling." (PMID 35417711, 2022). "To further determine whether this CD2-mediated inhibition of HIV-1 early infection steps can be alleviated by lymphatic cytokines, we cultured resting CD4 T cells in IL-2 or IL-7 for 3 days and then latently infected cells with HIV-1." (PMID 34765923, 2021). "Changes of cytokines IL‐1β, IL‐5, IL‐7, and IL‐12p40 within 6 hours after infection in the animal model were not significantly different between the two types of bacteria infected groups." (PMID 34725873, 2021). "DC isolated early after infection of pigs with either of the two CSFV strains showed prominent upregulation of CCL5, CXCL9, CXCL10, CXCL11, and XCL1, as well as of the cytokines TNFSF13B, IL6, IL7, IL12B, IL15, IL27." (PMID 32733474, 2020). "Patients with prolonged arthralgia during MAYV infection show that levels of IL-1Ra, IL-6, IL-7, IL-8, IL-13, IL-17, G-CSF, IFN-γ, PDGF- α, VEGF and IL-12p70 remained elevated up to 12 months after infection." (PMID 31050676, 2019). "In fact, both patients who developed infections in the RACS group had more pronounced elevated baseline-adjusted IL-7 at 72 h (ΔIL-772h/0 = 287%) than patients without infection (127%, P = 0.018)." (PMID 29904108, 2018). "Research has firmly established that infection by human immunodeficiency virus (HIV) leads to structural disruption in secondary lymph organs (SLOs) and that IL-7 expression by SLOs is downregulated in simian immunodeficiency virus (SIV)-infected rhesus macaques." (PMID 27011165, 2016). "Thus, given the fact that IL-7 supports the emergence and survival of memory CD4+ and CD8+ T lymphocytes, the differential CD127 expression in the early stages of infection can be partly responsible for viral persistence." (PMID 24465502, 2014). "The authors reported that the infection of normal human fibroblasts (NHF) with Ad-REIC did not cause the apoptosis of NHF itself, but instead induced the production of interleukin (IL)-7." (PMID 24498395, 2014). "IL-7 secretion by LEC is enhanced during lymphopenia, LN remodeling, and revascularization after transplant, and this assists in re-establishing normal LN architecture and cellularity after an infection or other perturbation." (PMID 25580369, 2014). "On average, IL-7 25 ng/mL increased the number of HIV-1-infected CD4+ (CD8− p24gag+) T cells in HIV-1LAI.04- and HIV-1BaL-infected lymphoid tissues 4.1±0.4 fold and 7.7±1.8 fold, respectively, on day 9 post infection (n = 8 and 6, p<0.001)." (PMID 23408885, 2013). "The recent identification of the liver as an IL-7 producing tissue upon TLR stimulation makes it tempting to speculate that HCV-infection can also, through TLR activation, stimulate IL-7 production by the liver." (PMID 22529911, 2012).
infection (continued). "This phenomenon was more prominent among IL-7-treated animals, as indicated by a significant difference in the proportion of the various functional subpopulations of Tat-specific CD8+ T cells on day 62 post-infection." (PMID 22511868, 2012). "However, on day 62 post-infection, CM CD8+ T cells returned to baseline values, while TM and EM CD8+ T cells were significantly decreased in both IL-7-treated and untreated animals." (PMID 22511868, 2012). "While in untreated animals all memory CD4+ T-cell subsets (CM, transitional memory [TM] and effector memory [EM]) dramatically declined during the acute phase of infection, none of these subsets was quantitatively reduced in animals receiving IL-7." (PMID 22511868, 2012). "To do this, we cultured untreated resting CD4+T cells or prestimulated the cells for 3 days with IL-7, CCL19, or CD3/28 beads and then spinoculated the cells with HIV, after which we measured the ratio of integrated to total HIV DNA 48 hours post infection." (PMID 22911005, 2012). "After 48 h of infection, MVA-B induced higher production of IL-7, IL-15, MCP-1/CCL2 and MIG/CXCL9 than uninfected MDDC, indicating that some mediators are secreted at later times post-infection and/or at low doses possibly because is necessary some degree of maturation to up regulate such mediators." (PMID 21625608, 2011). "IL-7 and IL-15 were detected previously after MVA infection of HeLa cells." (PMID 21625608, 2011). "Because IL-7 can increase the survival of T cells, we tested whether CD4+ T cells in HIS mice would be rescued by IL-7 following infection by HIV." (PMID 20700454, 2010). "We have not observed a similar role of Vpx in the infection of other non-dividing cell types such as macrophages or IL7-stimulated PBLs, although Vpx had a minor stimulating effect on the former cell type." (PMID 17212817, 2007). "In addition, some studies found that the levels of IL‐2, IL‐4, IL‐6, IL‐7, IL‐10, IP‐10, MCP‐1, TNF‐α, MIP‐1α, IFN‐γ, and G‐CSF in patients with severe COVID‐19 infection were significantly higher than those in patients with mild and moderate infection." (PMID 36684101, 2023). "Others, such as IL-1α, IL-2, IL-7, IL-9, IL-10, IL-12p40, IL-13, and VEGF were present at equivalent concentrations in lungs of infected and control mice during the first 5 days, but at significantly reduced concentrations in lungs of infected mice at day 7 post-infection." (PMID 35812400, 2022). "Moreover, after removing individuals with genital inflammation from the analysis, 11 of the biomarkers remained significantly higher in the pre-infection group compared to the uninfected group (Fractalkine, GMCSF, ITAC, IL-1ß, IL-6, IL-7, IL-8, IL-21, MIP-1α, MIP-3α, and TNFα)." (PMID 33731158, 2021). "Patients developing SSI had lower baseline IL-7 levels than patients without infection." (PMID 29904108, 2018). "In view of the biological activity attributed to IL-7, its persistent elevation in the early postoperative period following RACS may evoke beneficial immune responses and provide better protection against infection." (PMID 29904108, 2018). "Monitoring of plasma SIV viral loads throughout the IL-7 treatment periods found that RM22657 maintained viral control, and RM24090 failed to suppress, while RM23201 (191 d.p.i), RM23686 (134 d.p.i) and RM23750 (134 d.p.i) lost viral control (at the indicated dates post-infection)." (PMID 29261677, 2017). "The increased expression of pro-inflammatory interleukins and chemokines (e.g. interleukins, IL-8; IL-7; IL-1β; and C-X-C motif chemokine 10, CXCL10) parallels the transcriptional response of adult frog skin to the chytrid fungus Batrachochytridium dendrobatidis (BD) infection and entry." (PMID 28462779, 2017). "Also, IL-7 enhanced HIV-1BaL replication in human cervico-vaginal tissues, which predominantly support productive infection of R5 rather than X4 HIV-1 variants." (PMID 23408885, 2013).
infection (continued). "By normalizing to the infection level of each subset, we showed this clonal CCR5-restricted virus could be massively produced by TN cells, as well as by all memory subsets, especially when IL-7 was added to the stimulating cocktail." (PMID 23691172, 2013). "In the absence of IL-7 treatment, SIV infection caused significant decreases in the absolute numbers of naïve and memory CD4+ T cells, compared to pre-infection levels, throughout the acute phase of the infection." (PMID 22511868, 2012). "Treatment with IL-7 did not cause clinically detectable side effects and, despite the absence of concomitant ART, did not induce significant increases in the levels of SIV replication except at the earliest time point tested (day 4 post-infection)." (PMID 22511868, 2012). "Tissues that produce IL-7 include the generative lymphoid organs; however, the regulation of IL-7 production remains unclear but could be induced in nonlymphoid tissues upon infection." (PMID 22384197, 2012). "Furthermore, prior to the onset of infection we observed changes in IL-2 and IL-7 gene expression without any change in expression of the Bcl-2 related genes." (PMID 21711552, 2011). "Importantly, we demonstrate for the first time that MDDC infected with MVA and MVA-B, secrete IL-7 and IL-15 at levels more than 30-fold higher than the negative control after 48 h post-infection without maturation cocktail." (PMID 21625608, 2011). "Taken together, our data suggests that IL-7 and IL-15 have overlapping roles in mediating up-regulation of Bcl-2 and CD127 on antigen-specific CD8+ T cells and that differential CD127 expression does not impede CD44 expression or effector functions during acute phase infection." (PMID 20520779, 2010). "Furthermore, IL-7 and VEGF were also identified as potential mediators as they were significantly elevated at all time points in patients with chronic arthralgia but only elevated in the convalescent stage (IL-7), or at 3 and 12 months post-infection (VEGF) in the fully recovered patients." (PMID 39205271, 2024). "Furthermore, the involvement of up-regulated IL7 and IL1R2 in cytokine-cytokine receptor interaction pathway revealed in this study, may be involved in the induction of the inflammatory response against ETEC-F4ac infection." (PMID 32174961, 2020). "The lack of detection of VEGF-C, VEGF-D, IL-3 or IL-7 may be because we were examining the production of these molecules by PBMCs which may not be the cellular source; these molecules may be produced by a cell found focally at the infection site." (PMID 25010672, 2014). "In contrast, IL-1RA, IL-7, IL-13, and G-CSF were decreased in the merged SIDS cases compared to control cases without evidence of infection." (PMID 35986144, 2023). "IL7 and IL17 were elevated at baseline in aged mice compared to controls, which did not further enhance after infection." (PMID 35798721, 2022). "Plasma levels of six cytokines (IL-2, IL-3, IL-4, IL-7 and VEGF) were not significantly altered by Kp-1705 infection nor were they affected by MTD12813 treatment." (PMID 34873199, 2021). "In lymphoid tissues treated overnight with IL-7 25 ng/mL prior to infection with HIV-1LAI.04 and subsequently cultured in the absence of IL-7, HIV-1 replication was increased on average 3.1±0.6 fold (n = 4, p<0.05)." (PMID 23408885, 2013). "In addition, the relative level of several cytokines such as IL-5, IL-10, IL-7, IL-13 and Basic-FGF was not as impacted by the infection as the other chemokines/cytokines." (PMID 31391513, 2019). "The protective effects of IL-7 on memory CD4+ T cells were not sustained after treatment interruption as shown by the significant decline of all three subpopulations, compared to baseline, on day 62 post-infection." (PMID 22511868, 2012).
infection (continued). "Testing this further, we found that infection also downregulated the IL-7 receptor α subunit (CD127) from the cell surface and transcriptionally (fold change = 0.693, adjusted p = 5.89 × 10−8), collectively indicative of HIV-1 inducing enhanced JAK-STAT signaling even in the absence of IL-7." (PMID 35417711, 2022). "Importantly, Vpr also mediated STAT5-activation during HIV-1 cell-to-cell infection of resting memory CD4+ T cells as evidenced by an increase in the intracellular levels of phosphorylated STAT5 (P-STAT5) under conditions where cells were not exposed to IL-7." (PMID 35417711, 2022).
infectious disease (16 papers, 2010 to 2026). A disorder directly resulting from the presence and activity of a microbial, viral, or parasitic agent in humans. "Given the multiple beneficial immune effects that IL-7 can mediate in both settings of oncology and infectious disease, the continued clinical development of IL-7 combination studies holds great promise." (PMID 41550947, 2025). "Interleukin-7 (IL-7) and its receptor (IL-7R) play a very important role in the differentiation and growth of immune cells, and they have alternative splicing in infectious diseases." (PMID 38675618, 2024). "Administration of IL-7 increases both circulating and tissue lymphocytes, and for this effect it is currently under clinical trials for oncologic and infectious diseases." (PMID 36287942, 2022). "IL-7 is a pleiotropic cytokine, currently studied in clinical trials for oncologic and infectious disorders." (PMID 34540715, 2021). "IL‐7 is under investigation as an immunotherapy for infectious diseases." (PMID 41523740, 2026). "To investigate a safe and effective approach for enhancing the in vivo expression of recombinant genes and improving the systemic immunity of animals against infectious diseases, we employed the interleukin-7 (IL-7) gene from Tibetan pigs to construct a recombinant eukaryotic plasmid (VRTPIL-7)." (PMID 37237481, 2023). "Both IL-7 and anti-PD-L1 have been used in patients with various infectious disorders." (PMID 29944697, 2018). "We searched for nonsynonymous, essential splice site, or copy number variants of IL7 by screening our in-house whole-exome sequencing/whole-genome sequencing (WES/WGS) database of over 23,000 patients with various infectious diseases." (PMID 39352394, 2024). "This is the first report that demonstrates in an infectious disease model that lack of both IL-7 and IL-15 not only down-regulates the development of CD127hi subset, but also reduces the frequency of CD127hi cells expressing Bcl-2." (PMID 20520779, 2010). "As role of IL-7 and IL-15 alone in mediating CD8+ T cell proliferation has been recently demonstrated in non infectious disease models, next, we determined if reduced CD8+ T cell response in anti IL-7 treated KO mice infected with T. gondii is due to defect in their proliferative ability." (PMID 20520779, 2010). "IL-2 has been recently linked to improved secondary proliferation, while the role of IL-7 in maintenance of CD4+ memory cells has been demonstrated in homeostatic proliferation, but its role in protective memory populations in infectious disease protective has not been fully investigated." (PMID 22039531, 2011).